CDK17 (cyclin dependent kinase 17)
Description:
May play a role in terminally differentiated neurons. Has a Ser/Thr-phosphorylating activity for histone H1 (By similarity).
Synonyms: PCTAIRE2; PCTK2
Tractability: Small molecule: a drug acting on it is in phase 2 or 3 trials; a high-quality ligand is known; it belongs to a druggable protein family. PROTAC: it is named in the literature on targeted protein degradation; ubiquitination databases record sites on it; its protein half-life has been measured; a small molecule that binds it is known.
Target class: Protein Kinase; Enzyme; Kinase; CMGC protein kinase group; CMGC protein kinase CDK family; CMGC protein kinase PCTAIRE
Chemical probes: JA397 (high quality)
Gene: Protein-coding gene on chromosome 12 (96,278,242 to 96,400,562, reverse strand). Ensembl gene ENSG00000059758.
Subcellular location (Human Protein Atlas): Cytosol; Nucleoplasm
Gene Ontology:
Molecular function: protein binding; cyclin-dependent protein serine/threonine kinase activity; protein kinase activity; ATP binding; protein serine kinase activity
Biological process: protein phosphorylation; regulation of cell cycle phase transition
Cellular component: cyclin-dependent protein kinase holoenzyme complex; cytoplasm
Genetic constraint (gnomAD): Loss-of-function variants: 7 observed, 21.85 expected, observed/expected ratio (o/e) 0.32, 90% interval 0.18 to 0.6. The upper end of that interval is the gene's LOEUF score, 0.6, which puts it in group 2 of 6, group 1 being the genes least tolerant of losing a copy. Missense variants: 152 observed, 219.12 expected, observed/expected ratio (o/e) 0.69, 90% interval 0.61 to 0.79. Synonymous variants: 65 observed, 72.04 expected, observed/expected ratio (o/e) 0.9, 90% interval 0.74 to 1.11.
Homologues: Orthologues: macaque CDK17 (100% identical), rabbit CDK17 (99% identical), guinea pig CDK17 (99% identical), mouse Cdk17 (99% identical), chimpanzee CDK17 (98% identical), dog CDK17 (98% identical), pig CDK17 (98% identical), rat Cdk17 (96% identical), tropical clawed frog cdk17 (95% identical), zebrafish cdk17 (92% identical). Paralogues in human: CDK16 (68% identical), CDK18 (63% identical), CDK14 (40% identical), CDK15 (36% identical), CDK11B (36% identical), CDK11A (35% identical), CDK13 (34% identical), CDK12 (34% identical), CDK5 (31% identical), CDK1 (31% identical), CDK2 (30% identical), CDK3 (30% identical), and 14 more.
Diseases named in the same sentence as CDK17 in open-access papers:
CDK17 is named in the same sentence as 11 diseases in open-access papers, as found by Europe PMC text mining. Sharing a sentence is not in itself a finding about the gene and the disease. The quoted sentences say what the papers report.
glioma (2 papers, 2017 to 2024). A benign or malignant brain and spinal cord tumor that arises from glial cells (astrocytes, oligodendrocytes, ependymal cells). "Furthermore, genetic data from TCGA datasets show that CDK17 exhibits focal copy number deletions, missense, and frameshift mutations in low-grade glioma (LGG) and glioblastoma (GBM), further supporting its potential as a tumor suppressor in brain cancers." (PMID 38951876, 2024). "CDK17, on the other hand, shows its highest expression in Low-Grade Glioma (LGG) and CDK18 reaches its peak in renal clear cell carcinoma (KIRC)." (PMID 38951876, 2024). "According to the analysis, we found that only the downregulation of CDK17, GNA13, PHF21A, and MTHFD2 was closely associated with a decreased overall survival among patients with glioma." (PMID 29362722, 2017). "Survival analysis found that CDK17, GNA13, PHF21A, and MTHFD2 are closely associated with glioma." (PMID 29362722, 2017). "Up to now, the biological functions of CDK17, GNA13, PHF21A, and MTHFD2 in glioma have remained unclear." (PMID 29362722, 2017). "According to the study, downregulation of CDK17, GNA13, PHF21A, and MTHFD2 can be considered as biomarkers or therapeutic targets for glioma." (PMID 29362722, 2017). "The results suggested that CDK17, GNA13, PHF21A, and MTHFD2 might play important roles and potentially be valuable in the prognosis and treatment of glioma." (PMID 29362722, 2017).
cervical cancer (1 paper, 2024). A primary or metastatic malignant neoplasm involving the cervix. "The connection between CDK17 and QKI is further supported by the finding that circular RNA produced at the CDK17 locus (circCDK17) is overexpressed in cervical cancer, and it functionally regulates disease progression." (PMID 38951876, 2024).
glioblastoma (1 paper, 2024). The most malignant astrocytic tumor (WHO grade IV). "Bioinformatic analyses have highlighted CDK17 as one of the hub genes in glioblastoma, where its high expression is associated with better patient prognosis." (PMID 38951876, 2024).
pancreatic adenocarcinoma (1 paper, 2024). "CDK17 exhibits high expression in several tumor samples compared to their normal counterparts, including cholangiocarcinoma (CHOL), diffuse large B-cell lymphoma (DLBC), pancreatic adenocarcinoma (PAAD), and thymoma (THYM)." (PMID 38951876, 2024).
cancer (3 papers, 2018 to 2024). A tumor composed of atypical neoplastic, often pleomorphic cells that invade other tissues. "Among all PCTAIRE family members, CDK17 is the least explored in the context of cancer, although some intriguing findings have already emerged." (PMID 38951876, 2024). "Relatively more studies have attempted to address the role of CDK18 in cancer progression, compared to CDK17." (PMID 38951876, 2024). "CDK 17, also known as PCTAIRE-2/PCTK2, was not studied much in cancer." (PMID 33868579, 2021).
tumor (3 papers, 2023 to 2025). "This search revealed Dihydroartemisinin as the tumor suppressor by targeting CDK17,8; on the other hand, it demonstrated Imatinib9 and Bosutinib10 as potential antagonists against CDK2." (PMID 39929880, 2025). "This suggests a potential tumor-suppressive role for CDK17 in brain malignancies." (PMID 38951876, 2024).
CDK17 also shares sentences with these, for which no sentence is quoted: Alzheimer disease (3 papers); Azoospermia (1); brain cancer (1); breast carcinoma (1); thymoma (1).